GPC1 (glypican 1)
Diseases named in the same sentence as GPC1 in open-access papers (continued):
Sharing a sentence is not in itself a finding about the gene and the disease.
bladder cancer (4 papers, 2019 to 2023). "Recent studies in animal models and clinical studies in cancer patients resemble potential of using anti-GPC1 antibody for detection of bladder cancer using fluorescence imaging or utilizing GPC-1 directed radioimmunotherapy in different solid tumors." (PMID 36944188, 2023). "Here, treatment with an in house made GPC1 antibody decreased proliferation of T24 bladder carcinoma cells and HepG2 liver hepatocellular carcinoma cells." (PMID 36944188, 2023). "In vitro investigations by overexpression of GPC1 protein in T24 bladder carcinoma cells resulted in augmented proliferation." (PMID 36944188, 2023). "High expression levels of FOXO3, EGFR, and GPC1 as well as low expressions of VEGFA were closely correlated with poorer survival outcomes of bladder cancer patients." (PMID 33962639, 2021). "Two negative control cell lines were chosen that expressed differing densities of GPC-1 on their surface; the B cell lymphoma Raji (261 GPC-1 molecules per cell), and bladder cancer line C3 (approximately 3500 molecules per cell)." (PMID 33302918, 2020). "A monoclonal antibody MIL-38 had shown high affinity to Glypican-1, which is expressed by urinary bladder cancer cells and has a potential to deliver nanoconjugates to urothelial carcinoma cells." (PMID 31816991, 2019). "In this study, we demonstrated the production of targeted upconversion photoluminescent nanoconjugates UCNP@SiO2-LPG-MIL-38 for photodynamic diagnosis of bladder cancer cells and assessed their selectivity and molecular specificity towards Glypican-1 positive urothelial carcinoma cells T24." (PMID 31816991, 2019). "Specifically, we knocked-out exon 1 of GPC1 with CRISPR/Cas9GPC1 and transiently interfered with GPC1 transcript using siRNAGPC1 in cancer cells from patients with urinary bladder carcinoma (T24 cells), malignant brain glioma (U87 cells) and liver hepatocellular carcinoma (HepG2 cells)." (PMID 36944188, 2023). "In contrary, repression of GPC1 gene expression in T24 bladder carcinoma, HepG2 liver hepatocellular carcinoma and U87 brain glioma cells using CRSPR/Cas9 or siRNA resulted in significant attenuation of cancer cell proliferation indicating the potential of GPC1 as target for future cancer therapies." (PMID 36944188, 2023).
gastric cancer (4 papers, 2016 to 2025). A primary or metastatic malignant neoplasm involving the stomach. "EVs derived from stomach cancer cells encapsulate proteins such asclaudin-7, CD44v6, CD44, c-MET, EGFR, EpCAM, and GPC1, all of whichare closely associated with the progression of gastric cancer." (PMID 40720603, 2025). "The proteoglycans syndecan-1, syndecan-2, syndecan-4, glypican-1 and glypican-3 were upregulated in gastric cancer with high in vitro and in vivo peritoneal seeding potential, suggesting a role for these molecules in peritoneal dissemination." (PMID 27074785, 2016). "Our data revealed that only GPC1, GPC4, and GPC5 were expressed in MKN74 gastric cancer cells." (PMID 36181793, 2022).
lung adenocarcinoma (4 papers, 2019 to 2024). A carcinoma that arises from the lung and is characterized by the presence of malignant glandular epithelial cells. "Of note, GPC1 and S100A2 have been previously reported together as candidate biomarkers associated with unfavorable prognosis in lung adenocarcinoma without however relationship between the two molecules inferred." (PMID 36944188, 2023).
melanoma (4 papers, 2016 to 2023). A malignant, usually aggressive tumor composed of atypical, neoplastic melanocytes. "Glypican 1 has been shown to be a target of miR-149 in cell types including melanoma cells and endothelial cells." (PMID 34692689, 2021). "Moreover, F13A1 and GPC1 are biomarkers for melanoma metastasis." (PMID 37158593, 2023).
neuroblastoma (4 papers, 2009 to 2023). Neuroblastoma (NB) is the most common solid, extracranial childhood tumor. "In addition, we show that glypican-1 directly interacts with both PrPC and PrPSc and that depletion of glypican-1 in scrapie-infected murine neuroblastoma N2a (ScN2a) cells inhibits the formation of PrPSc." (PMID 19936054, 2009). "To address whether glypican-1 was also able to interact with PrPSc we performed co-immunoprecipitation experiments using cell extracts prepared from mouse neuroblastoma cells persistently infected with PrPSc (ScN2a cells)." (PMID 19936054, 2009). "It has been previously demonstrated that GPC1 may be localized in lipid rafts of neuroblastoma cells or myoblasts; however, there were no previous data of this PG in GBM cells." (PMID 32180897, 2020).
ovarian carcinoma (4 papers, 2018 to 2025). A malignant neoplasm originating from the surface ovarian epithelium. "Indeed, individual glypicans have been identified as prognostic factors in oesophageal squamous cell carcinoma (GPC1), hepatocellular carcinoma (GPC3) and ovarian cancer (GPC6)." (PMID 33742285, 2021).
pancreatitis (4 papers, 2017 to 2025). Inflammation of the pancreas. "Additionally, they found that GPC1‐positive exosomes failed to adequately distinguish between PC and pancreatitis." (PMID 36660044, 2022). "Finally, we evaluated GPC1 mRNA levels in human serum EVs from PDAC patients at stage I–II (n = 86), stage III–IV (n = 32), benign pancreatic disease (BPD, n = 15; patients with pancreatitis), and healthy donors (n = 60) in a discovery study." (PMID 29162835, 2017).
Alzheimer disease (3 papers, 2019 to 2022). A progressive, neurodegenerative disease characterized by loss of function and death of nerve cells in several areas of the brain leading to loss of cognitive function such as memory and language. "GPC1 is involved in the tumorigenesis of several tumor types, including PDAC, and several reports suggest a link between GPC1 and neurodegenerative diseases such as Alzheimer’s disease, prion disease, and Niemann–Pick-type C1 disease." (PMID 36142190, 2022). "Supermeres are highly enriched with cargo involved in multiple cancers (glycolytic enzymes, TGFBI, miR-1246, MET, GPC1 and AGO2), Alzheimer’s disease (APP) and cardiovascular disease (ACE2, ACE and PCSK9)." (PMID 34887515, 2021). "Gpc1 is unlikely to be the sole mechanism by which miR-324-5p exerts any effects on the nervous system, and in fact we found that miR-324-5p can also inhibit App expression; a gene whose protein contributes to brain pathogenesis, such as in Alzheimer's disease." (PMID 30193893, 2019).
colorectal tumors (3 papers, 2015 to 2023). "Our analysis of primary human colorectal tumors stressed by radiochemotherapy treatment shows that one consequence of therapy could be a similar increase in the distribution of Wnt ligands through upregulated expression of glypicans (e.g., GPC1) and SFRP proteins." (PMID 28183841, 2017). "Glypican-1 and Glypican-3 dysregulation is related to Notum and β-catenin alterations mostly in AOM/DSS-induced colorectal adenocarcinomas and in human colorectal tumors but also, in some cases, in early murine CRC stages." (PMID 26517809, 2015).
liver cancer (3 papers, 2020 to 2024). An epithelial or non-epithelial malignant neoplasm that arises from the liver. "Although the bioinformatic analysis WGCNA analysis also give us some strong insights into GPC-1 in liver cancer, more biological experimentation is needed to verify our findings and promote clinical utility." (PMID 38982153, 2024). "Raw data from TCGA, GTEx and TIMER databases were utilized to comprehensively analyze GPC-1 expression landscape in pan-cancer, and the biological function of GPC-1 was investigated in liver cancer cells." (PMID 38982153, 2024). "Gpc3 has been reported to modulate WNT and HH signaling in liver cancer and interestingly, GPC3 was previously found to interact with BMP2, like the not differentially expressed GPC1, to regulate suture fusion." (PMID 37378024, 2023).
metastatic carcinoma (3 papers, 2019 to 2024). A carcinoma which has spread from the original site of growth to another anatomic site. "Only 5 of 23 resected cancer patients and 9 of 30 metastatic cancer patients had mean GPC1 EV counts higher than the mean counts observed in BPD patients." (PMID 30800217, 2019). "Combined analysis with GP2 was intended to improve the effectiveness of our EV-based test, however an even lower number of metastatic cancer patients exhibited elevated GPC1-GP2 EV counts compared to mean counts in BPD patients than GPC1 EV counts (2 of 30 patients compared to 9 of 30 patients)." (PMID 30800217, 2019). "In addition, we observed high protein expression levels of GPC-1 in metastatic cancer cell lines such as DU-145 and PC-3." (PMID 31391540, 2019).
neuroendocrine tumors (3 papers, 2014 to 2017). "In neuroendocrine tumors, about 80% of cases showed GPC1 expression (14/17)." (PMID 29245923, 2017). "Interestingly, in neuroendocrine neoplasias derived from the large bowel, GPC1 expression has been shown to be intense in well-differentiated tumors, but far less in poorly differentiated, a feature that seems to be shared with other neuroendocrine tumors, independently of their topography." (PMID 26482785, 2015).
oesophageal cancer (3 papers, 2020). "GPC-1 expression may be weaker in pancreatic than oesophageal cancer, and its roles may differ in each case." (PMID 32152502, 2020). "Compared to its high expression in human esophageal carcinoma, normal tissues showed low to no expression of GPC1 when stained with anti-GPC1 mAb (clone: 1–12)." (PMID 32228854, 2020).
prion disease (3 papers, 2009 to 2022). A transmissible disease that is caused by a protein that is able to induce abnormal folding of normal cellular proteins, leading to characteristic spongiform brain changes, which are associated with neuronal loss without an inflammatory response. "Our results indicate that glypican-1 is intimately involved in the misfolding of the prion protein, the critical event in the pathogenesis of prion diseases such as Creutzfeldt-Jakob disease in humans." (PMID 19936054, 2009). "Targeting of both prions through glypican-1 facilitates favorable interaction of PrPSc with PrPc within membrane rafts, which are believed to be the conversion sites of PrPc to PrPSc, suggesting a critical role of glypican-1 in the pathogenesis of prion disease." (PMID 22191032, 2011). "Following from these results, the design of specific small molecule inhibitors to antagonise the binding of glypican-1 and PrPC/PrPSc may represent a viable therapeutic avenue for the treatment of prion diseases." (PMID 19936054, 2009).
acute myeloid leukemia (2 papers, 2022 to 2024). Acute myeloid leukemia (AML) is a group of neoplasms arising from precursor cells committed to the myeloid cell-line differentiation. "Since both FGF2 and GPC1 are key components of tumor progression for a wide range of cancer types, we propose that the prominent function of GPC1 in driving efficient unconventional secretion of FGF2 might play a key role for tumor development such as acute myeloid leukemia." (PMID 35348113, 2022).
injury (2 papers, 2021 to 2023). Damage inflicted on the body as the direct or indirect result of an external force, with or without disruption of structural continuity. "To test if Gpc1−/− lungs showed different susceptibility to a sepsis model of acute lung injury (ALI), we assessed their susceptibility to develop pulmonary edema, a known outcome of acute lung injury and ARDS, using sepsis model, in which mice were injected with LPS 10 mg/Kg, intraperitoneally." (PMID 37834029, 2023). "Slit2 and Glypican-1 are highly expressed and have been shown to interact in experimental models of brain injury, preventing regenerating axons from entering the lesioned area." (PMID 34066896, 2021).
intraductal papillary mucinous neoplasms (2 papers, 2017 to 2018). "In intraductal papillary-mucinous neoplasms (IPMNs), GPC1 tended to be positive in gastric-type IPMN." (PMID 29245923, 2017).
lymphoma (2 papers, 2020). A malignant (clonal) proliferation of B- lymphocytes or T- lymphocytes which involves the lymph nodes, bone marrow and/or extranodal sites. "Of specific interest, however, was the fact that lymphoma development occurred in the same animal that also displayed the highest average level of induction of GPC1 gene expression in d28 pi LN biopsy samples." (PMID 32017809, 2020). "Thus, a particularly intriguing finding was the fact that the highest induction of GPC1 gene expression was observed in animal 29119, the only animal in the entire cohort to develop lymphoma." (PMID 32017809, 2020). "Specifically, cells isolated from d0 and d28 pi LN biopsy and lymphoma tissue were stained with anti-GPC1 antibody, in conjunction with antibodies directed against CD20, CD3, and CD14, to determine the levels of GPC1+ cell subsets in these tissues." (PMID 32017809, 2020). "Flow cytometry demonstrated high expression of GPC-1 in both cell lines U-87 and U-251 compared to the GPC-1 negative lymphoma cell line, Raji." (PMID 32316186, 2020).
Sepsis (2 papers, 2019 to 2023). Sepsis is defined as life-threatening organ dysfunction caused by a dysregulated host response to infection. "We report for the first time that glypican 1, 3, and 4 levels are elevated in the plasma of patients with sepsis compared to those with infection without organ failure." (PMID 30618011, 2019).
squamous cell carcinoma (2 papers, 2018 to 2022). A carcinoma arising from squamous epithelial cells. "We found a group of tumor-specific WNT members, including a panel of squamous cell carcinomas (SCCs) specific upregulated WNT ligands and receptors, WNT5A, WNT7B, FZD7 and GPC1." (PMID 35850748, 2022). "We have previously shown that glypican-1 (GPC-1) was preferentially overexpressed on squamous cell carcinoma, and generated anti-GPC-1 human CAR-T cells (hGPC1-CART) using our anti-GPC-1 Ab which recognizes both human and murine GPC-1." (PMID 30400835, 2018).
acinar cell carcinoma (1 paper, 2017). "In acinar cell carcinomas, no GPC1 expression was observed (0/5)." (PMID 29245923, 2017).
alopecia (1 paper, 2021). Hair loss usually from the scalp. "Thus, GPC1 might constitute an interesting target to tackle alopecia in dermatology research." (PMID 34957110, 2021). "Thus, GPC1 might constitute an interesting target to tackle alopecia in cosmetology research." (PMID 34957110, 2021).
brachydactyly type E (1 paper, 2019). Brachydactyly type E (BDE) is a congenital malformation of the digits characterized by variable shortening of the metacarpals with more or less normal length phalanges, although the terminal phalanges are often short. "In humans the Glypican 1 gene has previously been identified as a possible candidate for causing Brachydactyly Type E, an inherited condition causing skeletal deformities." (PMID 30193893, 2019).
chronic kidney disease (1 paper, 2024). Impairment of the renal function secondary to chronic kidney damage persisting for three or more months. "The degradation of the GCX has been observed in renal diseases such as chronic kidney disease (CKD), where vascular injury from fibrosis resulted in the upregulation of proteoglycans syndecan-1 and glypican-1." (PMID 39125975, 2024).
COVID-19 (1 paper, 2023). A disease caused by infection with severe acute respiratory syndrome coronavirus 2. "In agreement, we demonstrated increased syndecan-1 and glypican-1 (albeit lower than syndecan-1 levels) shedding in COVID-19 patients, and protein concentrations were the highest in severe cases." (PMID 37147421, 2023). "In COVID-19 patients, we observed increased plasma MPO levels, MPO activity, syndecan-1 and glypican-1 concentrations to be associated with severe disease." (PMID 37147421, 2023). "At acute and convalescent phases, COVID-19 positive subjects had significantly higher syndecan-1 [acute (p < 0.01); convalescent (p < 0.05)] and glypican-1 [acute and convalescent both p < 0.01)] breakdown compared with controls [both proteins below limit of detection]." (PMID 37147421, 2023). "Like previous findings, COVID-19 plasma treatment on primary endothelial cells induced soluble EG shedding, however, differences in syndecan-1 shedding but not glypican-1 disruption was more prominent between COVID-19 severity." (PMID 37147421, 2023). "Analysing a subset of acute and convalescent COVID-19 plasma, 10 from severe and 15 from non-severe COVID-19 cases, and 9 from pre-COVID-19 controls, we determined MPO levels, MPO activity and soluble EG proteins (syndecan-1 and glypican-1) levels by enzyme-linked immunosorbent assay." (PMID 37147421, 2023).
dementia (1 paper, 2025). Loss of intellectual abilities interfering with an individual's social and occupational functions. "Despite most of these being more prominently dysregulated in AD (e.g., SDC4, ITGB2, MIF, and sTREM1), a small subset of proteins showed an opposite effect between these dementias (e.g., CHL1, GPC1, and CNTN5)." (PMID 40866991, 2025).
diabetes (1 paper, 2011). "The increased amount in diabetes of glypican-1 and syndecan-4 is somewhat expected, because these proteoglycans modulate the interaction of FGF, augmented in diabetes, with different receptors and protect it against inactivation." (PMID 21518435, 2011). "The aim of this study was to investigate in vivo heart function changes and alterations in mRNA expression and protein levels of glypican-1 and syndecan-4 in cardiac and skeletal muscles during streptozotocin (STZ)-induced diabetes." (PMID 21518435, 2011). "For this purpose, we examined the mRNA expression and the amount of 2 key cell surface heparan sulfate chain-carrying core proteins, syndecan-4 and glypican-1, after 24 hours, 10 days, and 30 days of STZ-induced experimental diabetes in 2 muscles, cardiac and skeletal." (PMID 21518435, 2011).
diabetic cardiomyopathy (1 paper, 2016). Diabetic cardiomyopathy is a disorder of the heart muscle in people with diabetes. "Membrane proteoglycans Gpc3 and Sdc1 have not yet been demonstrated to play a role in the development of diabetic cardiomyopathy, however, increased expression of the heparan sulfate proteoglycans Gpc1 and Sdc4 has been shown to lead to diastolic dysfunction in streptozotocin-induced diabetic rats." (PMID 27496100, 2016).
epilepsy (1 paper, 2025). A brain disorder characterized by episodes of abnormally increased neuronal discharge resulting in transient episodes of sensory or motor neurological dysfunction, or psychic dysfunction. "Although no clear relationship between GPC1 and epilepsy has been described, another member of the same proteoglycan family, GCP4, has been reported to promote mossy fiber sprouting after pilocarpine-induced status epilepticus via mTOR." (PMID 40076950, 2025).
glomerulosclerosis (1 paper, 2011). A hardening of the kidney glomerulus caused by scarring of the blood vessels. "The percentage of glomeruli with global glomerulosclerosis in each biopsy specimen correlated to the expression of the proteoglycan glypican-1 in the glomerular fraction (r = 0.57, n = 18, p<0.05)." (PMID 21494642, 2011). "Decorin (n = 15, r = 0.64, p<0.05) and glypican-1 (n = 15, r = 0.79, p<0.001) gene expression in the tubulo-interstitium also correlated to presence of global glomerulosclerosis." (PMID 21494642, 2011).
Heat Stroke (1 paper, 2025). A condition caused by the failure of body to dissipate heat in an excessively hot environment or during PHYSICAL EXERTION in a hot environment. "Heat stress induces glycocalyx shedding, as evidenced by fluorescence staining revealing diminished expression of glypican-1 (GPC-1) and SDC-1 in pulmonary vascular endothelia following heat stroke." (PMID 40703654, 2025).